APC (APC regulator of Wnt signaling pathway)
Diseases named in the same sentence as APC in open-access papers (continued):
Sharing a sentence is not in itself a finding about the gene and the disease.
colon carcinoma (continued). "However, only 5.5% of colon cancers have mutations both in APC and RNF43, suggesting a differential mechanism of optimal activation of Wnt signaling in gastric and colon cancers for tumor growth and progression." (PMID 34552611, 2021). "Finally, we investigated the effect of the combinatory targeting of Wnt and YAP in a well-established DSS-induced colon cancer model using APC-MIN mice." (PMID 34298652, 2021). "Also, the changes in expression of the APC protein that is related to the alterations in expression of the APC gene lead to promoting colon cancer due to the abnormalities in cell cycle." (PMID 34711004, 2021). "Quantification of c-MYC (oncogene) and APC (tumor suppressor) mRNA levels help elucidate how the A. mexicana root methanol extract may be affecting colon cancer cells." (PMID 33826680, 2021). "CAF-derived Wnt2 activates canonical signaling in APC/β-catenin wild-type colon cancer cells (but not in cells with APC/CTNNB1 mutations) in a paracrine manner." (PMID 33276489, 2020). "While more than 70% of human colon tumors have mutations in APC, a common early event in the evolution of human colon cancer, neither of the two colon syngeneic mouse models that we studied contain APC mutations." (PMID 31898484, 2020). "To examine, whether Wnt signatures differ also between human colon cancer samples from different locations, we compared again MSS tumours with a mutation in APC from TCGA data." (PMID 33292279, 2020). "APC, SMAD4, NF1 (neurofibromin 1), ARID5B, NCOR1 (nuclear receptor corepressor 1), IGFR1R (insulin like growth factor 1 receptor) and GNAS (GNAS complex locus) were the most often mutated genes in patient-derived colon cancer cells." (PMID 33050525, 2020). "Furthermore, we demonstrated that p22 can increase TCF/β-catenin transcription on its own and in conjunction with ectopically expressed wild-type or mutant β-catenin; and in colon cancer cells with endogenous mutant APC (SW480 cells) or CTNNB1 (HCT116 cells)." (PMID 32486480, 2020). "A role for APC in the development of colon cancer has been reported; thus, we focused on TIMP2." (PMID 32118353, 2020). "In APC we detected the frequent c.3920T>A, p.(Ile1307Lys) variant in a woman with colon cancer at age 47 years (no. #6;142)." (PMID 33193653, 2020). "Thus, to investigate the effect of p22 in cancer cells with endogenous mutations to intracellular Wnt pathway components, we used colon cancer cell lines SW480 and HCT116 that harbor truncated APC and mutated β-catenin, respectively." (PMID 32486480, 2020). "Having observed Wnt-mediated re-localization of the β-catenin destruction complex in human colon cancer cell lines, we wondered if normal human colon stem cells also displayed this property and if so, whether this relocalization was APC-dependent." (PMID 32076059, 2020). "Nevertheless, the finding is consistent with low levels of Axin2 and other Wnt target genes as well as the lack of APC mutation in MSI-H colon cancer cells with BRAF-V600E mutation." (PMID 31811196, 2019). "Similar results were observed in an APC-driven colon cancer model." (PMID 30996297, 2019). "Combined, these studies collectively do not support the hypothesis that expression of PPARβ/δ is increased by APC/β-CATENIN/TCF4 signaling in colon cancer, as both the mouse and human models examined include those with defective APC signaling." (PMID 31602402, 2019).
colon carcinoma (continued). "CMS2 subtype colon cancer patients were characterized by the activation of WNT signaling pathway, however, we did not observe high frequency of APC mutation in CMS2 subtype derived from colon cancer cell lines neither." (PMID 31596728, 2019). "Examining a previously established collection of the normal colonic cells (HCEC) expressing the known oncogenic drivers of colon cancer such as truncated APC and mutant KRAS, we demonstrated that LEF1 was upregulated upon the expression of truncated APC and activated KRAS." (PMID 31623618, 2019). "Furthermore, loss of CDX 1 and/or CDX2 was shown to impact TGF beta signaling and tumor invasion in murine APC mutant colon cancer models." (PMID 30909444, 2019). "In colon cancer, RNF43 mutations were largely exclusive with APC mutation." (PMID 31811196, 2019). "Moreover, a strong association between mutations in APC and other genes such as KRAS or BRAF and colon cancer initiation has in fact been established." (PMID 31142796, 2019). "Carriers with mutations in the APC gene develop polyps in the colon and rectum which if not managed, transition into colon cancer." (PMID 30256815, 2018). "SW480 is a human colon cancer cell line with APC C-terminal truncation at 1338, but the β-catenin binding region is retained; HCT116 is a highly metastatic cell line with WT APC and both an S45 mutation and the WT allele for β-catenin, but most of the β-catenin protein comes from the mutant allele." (PMID 29337987, 2018). "The detection of relatively high levels of nuclear LMW pβ-Cat552 in colon cancer cells suggests that this pathway does not preclude the well-characterized degradation pathway altered by mutations in APC and β-catenin." (PMID 29330435, 2018). "In addition, this study provided evidence of some remarkable differences between CACs developed in CD and in UC patients: the frequency of both APC and IDH1 mutations was higher among CD- than UC-derived colon cancers." (PMID 29652830, 2018). "In this study, we used two colon cancer cell lines for the expression of truncated APC." (PMID 29549256, 2018). "Phosphorylation of APC by Bub kinases may be an important aspect of CIN phenotype, explaining why the loss of Bub1 kinase activity is a common feature of colon cancer cell lines." (PMID 28576136, 2017). "Thus, in APC Min mice, used as a model for human familial adenomatous polyposis, TZDs increase the number of colon tumors." (PMID 28298922, 2017). "USP7 inhibition significantly suppresses tumor growth of APC-mutated colon cancer cells but does not affect cells with wild-type APC, suggesting that it can be used as a tumor-specific drug target." (PMID 29045831, 2017). "Furthermore, restoring full length APC is sufficient to abrogate tumour growth in human colon cancer cells in vitro, or using a mouse model which allows deletion and restoration of Apc in vivo." (PMID 27196929, 2016).
colon carcinoma (continued). "The main finding of this study is that APC mutations, as could be detected by coverage of the TSACP analysis, were associated with a poor DFS in stage III MSS colon cancer patients (p = 0.005; HR = 4.1)." (PMID 27729614, 2016). "In 90% of the colon cancer cases, there is no familial history of colon cancer, however, sporadic colorectal cancer has many of the same genetic mutations, especially in the APC gene, that are somatically acquired during the life of an individual." (PMID 26959117, 2016). "We questioned whether DDX3 could activate the β-catenin/ZEB axis in APC-wild-type colon cancer cells." (PMID 27007150, 2016). "While mutations in the APC tumor suppressor gene were associated with a worse clinical outcome in stage III MSS colon cancer patients, this association was not encountered in stage II disease." (PMID 27729614, 2016). "Inhibition of DNA replication checkpoint by a Chk1 inhibitor could increase sensitivity of APC-mutant colon cancer cells." (PMID 27729614, 2016). "Taken together, APC genotypes play a key role in LPS induced different colon cancer biological response by cross-regulating β-catenin and NF-κB, which may provide a novel strategy for carcinogenesis prevention." (PMID 26760960, 2016). "Fodde (2003) found that in the HCT116 cell strain of human colon cancer cells expressing the overall length APC, although the C terminal domain of APC (including microtubule binding domain) could be expressed, the none-integer chromosome was also developed." (PMID 27065015, 2016). "Recently, increasing evidences have suggested that Wnt/β-catenin signaling plays an important role in lung carcinogenesis, which has much less APC and β-catenin mutations unlike colon cancers." (PMID 26910283, 2016). "HGUE-C-1 represents a novel and peculiar colon carcinoma model to study chemoresistance to chemotherapeutic agents and to novel anti-neoplasic drugs that interrupt signalling pathways such as the APC/βcatenin, Ras/Raf/Mek/Erk, PI3K/mTOR/p70S6K pathways as well as histone regulation mechanisms." (PMID 25885658, 2015). "We used two different doxycycline-induced shRNAs against CTNNB1 to study effects of antagonizing CTNNB1 endogenous transcript levels in the DLD1 human colon cancer cell line, which harbor APC defects leading to constitutive activation of β-catenin/TCF signaling." (PMID 26528816, 2015). "Zinc stabilizes APC levels and induces cell cycle arrest in colon cancer cells." (PMID 25878905, 2015). "Unlike colon cancer, neither APC mutation nor APC methylation seemed to be involved in gastric cancer." (PMID 26417932, 2015). "After showing the interaction between GRP78 and APC protein, we intended to investigate whether the APC protein could be secreted from colon cancer cells." (PMID 24977433, 2014). "Deletion of APC, a known tumor suppressor, is a key event in colon cancer progression." (PMID 25162504, 2014).
colon carcinoma (continued). "For instance, beside (loss of heterozygosity)LOH and hypermethylation, inactivation ofthe APC gene by mutation has been observed indifferent type of colon cancer, such as familialor sporadic and with or without polyposis." (PMID 24518971, 2014). "It follows that the 15R may contribute to the degradation of phosphorylated β-catenin and may provide the partial activity of truncated APC in colon cancer cells, as has been discussed recently." (PMID 24722208, 2014). "In order to investigate whether the expression of normal APC is necessary to produce the PKCδ inhibition effect, we made use of the colon carcinoma cell line HCT116." (PMID 23520519, 2013). "However, DKK-1 seems to have antitumor effects independent of β-catenin/TCF transcriptional inhibition, as DKK-1 overexpression in APC-mutant colon cancer cells decreases colony formation capacity in vitro and tumor growth in immunodeficient mice." (PMID 24202444, 2013). "Since the truncated APC protein is not fully functional, and leads to, via WNT, aberrant down-regulation of CPC protein expression, it is not surprising that APC mutations lead, in colonic tumors, to aberrantly oriented mitotic spindles and aneuploidy." (PMID 24224156, 2013). "Next, we asked whether β-catenin accumulation in colon cancer cell lines harbouring mutations impaired β-catenin degradation, for example HCT116 with β-catenin mutation or SW480/SW620 cells with APC mutation, was also dependent on SR proteins." (PMID 23592547, 2013). "A mutation in the APC gene is an early step in the tumorigenesis of colon cancer and is considered to be a hallmark of sporadic non-hereditary polyposis." (PMID 24179534, 2013). "Our aim was to compare the effects of Tcf-4 knockdown and β-catenin knockdown on cell proliferation, apoptosis, and chemosensitivity in the SW480 (mutant APC, wild-type CTNNB1) and HCT116 (mutant CTNNB1, wild-type APC) colon cancer cell lines using short hairpin RNA (shRNA)." (PMID 23029137, 2012). "It is widely accepted that most human colon cancers are initiated by the inactivation of the Adenomatous Polyposis Coli (APC)/Wnt signaling pathway and then progress as the result of a series of mutational activation of oncogenes coupled with the inactivation of tumor-suppressor genes." (PMID 22452792, 2012). "Data from mammalian cells initially suggested that this region of APC might be dispensable, as fragments of the central region of APC lacking the Arm repeats rescued Arm destruction in cultured human colon cancer cells." (PMID 22359584, 2012). "Interestingly, in normal colon cells, APC is strongly localized in the nucleus while appearing increasingly in the cytoplasm in colon carcinoma." (PMID 21390237, 2011). "Adenomatous Polyposis Coli (APC) is a tumor suppressor gene product involved in colon cancer." (PMID 21311754, 2011). "Additionally, expression of Pri-miR-25 in SW480 colon cancer cells, that exhibit high Wnt/β-catenin activity due to an APC truncation, significantly inhibited both the STF Wnt-reporter activity by ∼40% and β-catenin protein levels by 20%." (PMID 22043311, 2011). "Colon cancers with high levels of miR-135a and miR-135b show lower APC expression." (PMID 21403819, 2011). "Moreover, repression of SIRT1 in APC wild type colon cancer cells induced massive apoptosis in a FOXO4-dependent manner." (PMID 21698133, 2011). "While the underlying mechanism for this is unknown, a survey of the literature reveals that APC localization differs in colon cancer cells lines but follows a trend based on APC length." (PMID 19460168, 2009). "We report novel APC mutations and present two FAP cases that suggest familial aggregation of thyroid cancer and demonstrate the need to consider attenuated FAP also among elderly patients with colon cancer." (PMID 19036155, 2008).
colon carcinoma (continued). "Notably, TAGP can still induce β-catenin degradation in colon cancer cells harboring APC mutations, indicating that APC does not participate in this process." (PMID 40730487, 2025). "Therefore, the loss of the APC function is probably not sufficient to trigger colon cancer, but downstream signalling pathways that can be induced by sphingolipid alterations probably enhance the tumour-promoting effect." (PMID 38635059, 2024). "As introduced earlier, colon cancers occurring in the proximal and distal colon tend to exhibit distinctive genetic and epigenetic alterations, with those in proximal colon cancers more frequently harboring BRAFV600E mutations and being mutually exclusive of APC mutations." (PMID 38360902, 2024). "Epigenetic analysis showed that long-term exposure to high n-6 PUFA diets down-regulated APC expression through CpG hypermethylation, and was associated with increased COX-2 expression through PTSC-2 CpG hypomethylation, which increased the risk of inflammation and colon cancer." (PMID 36771436, 2023). "P2 had also developed colon cancer before, pointing at a predilection caused by the presence of APC mutations, albeit the germline status could not be evaluated." (PMID 36013219, 2022). "Interestingly, APC-wt MSS/pMMR colon cancer patients have a higher DCR for ICIs." (PMID 35937946, 2022). "For example, the LRP6 knockdown may have off-target effects specifically in APC-deficient HEK293 T cells and a number of APC-mutant colon cancer cell lines, and LRP6 knockdown in these cell lines further increased Wnt signaling instead of decreasing shown by Saito-Diaz." (PMID 34000297, 2021). "Notably, NTZ depleted β-catenin in colon cancer cells with mutant APC or β-catenin, For cancer treatment, a new use for an “old drug” has many benefits without the limitation of unknown safety and toxicity profiles." (PMID 33046820, 2021). "These suggest that APC mutation alone may not be a direct factor for colon tumor development in AOM/DSS-treated KAD rats as molecular mechanism of genetic mutation." (PMID 34003864, 2021). "Finally, we investigated whether the consumption of high-phenolic sorghum bran-containing diets influences tumor formation using a DSS-treated APC Min/+colon cancer genetic mouse model." (PMID 34361052, 2021). "Therefore, the APC mutant disrupts the sequestration of β-catenin by the destruction complex, thereby increasing its cellular levels and the consequent expression of mitogenic genes such as Myc and cyclin D, contributing to the pathogenesis of colon cancer." (PMID 34356615, 2021). "Adenomatous polyposis coli (APC), a gatekeeper tumor suppressor gene, is the most commonly mutated gene in familial adenomatous polyposis (FAP) that develops many colonic polyps and has the highest risk of developing colonic cancers at an early age (<35 years)." (PMID 33348563, 2020). "APC, SMAD4 (SMAD family member 4), NF1 (neurofibromin 1), ARID5B, NCOR1 (nuclear receptor co-repressor 1), IGFR1R (insulin like growth factor 1 receptor) and GNAS (GNAS complex locus) were the most often mutated genes in patient-derived colon cancer cells, YUMC-C1 and YUMC-C2." (PMID 33050525, 2020). "Our data also suggest that chronic exposure to an n-6HFD downregulates APC expression via CpG hypermethylation and this associates with increased expression of COX-2 via PTSG-2 CpG hypomethylation and accumulation of C-JUN and CCND1, thus increasing the risk of inflammation and cancer of the colon." (PMID 30650553, 2019).